RUNX3 (RUNX family transcription factor 3)
Diseases named in the same sentence as RUNX3 in open-access papers (continued):
Sharing a sentence is not in itself a finding about the gene and the disease.
tumor (continued). "The Runt-Related Transcription Factor-3 (RUNX3), which plays a significant part in cell proliferation, has been shown to play a tumor suppressor role in several types of cancers and its expression levels are downregulated in cancer." (PMID 32765634, 2020). "RUNX Family Transcription Factor 3 (RUNX3) is a downstream target of the TGF-β pathway, which is a tumor suppressor in pathway." (PMID 33401247, 2020). "Although RUNX3 was reported to be a tumor suppressor in CRC, in TCGA CRC dataset, RUNX3 expression displays weak difference between normal and cancer and weak correlation with prognosis (HR = 1.125, 95% CI: 0.965‒1.312)." (PMID 32717065, 2020). "Pathway analysis showed activation of the transforming growth factor-β pathway in YSTs, which is associated with the overexpression of GATA6 and FOXA2 and the hypermethylation of tumor-suppressor genes (e.g., RASSF1, RUNX3, HIC1, or APC)." (PMID 32999426, 2020). "The runt-related transcription factor-3 (RUNX3) gene, a noted tumor suppressor gene, regulates gene expression in some dominant developmental pathways and has antitumor activity in various types of tumors." (PMID 33575207, 2020). "Re-expression of RUNX3 promotes proliferation, anchorage-independent growth, and motility in KGN cells in vitro and tumor formation in mice in vivo." (PMID 31311113, 2019). "As a regulator of T cell development, Runx3 increases the amounts of tumor-infiltrating CD8+ T cells and restrains tumor growth." (PMID 31122259, 2019). "miR-106b is reported to promote the tumor growth through targeting tumor suppressor genes, such as Pten, Cdkn1a, E2F1, Setd2, Runx3, Smad7, Cdkn1a, and Bim." (PMID 31547867, 2019). "It is our future interest to develop mouse xenograft models by repeated in vivo passaging of these KGN/RUNX3 tumors in mice, in order to establish a KGN xenograft model with a faster tumor growth that would be suitable for therapeutic drug testing." (PMID 31311113, 2019). "When the expressions of RUNX3 and TGF-β were restored by treatment with 5-aza-2′-deoxycytidine before inoculation into the in vivo model, the tumor size was smaller and the animal survival time was prolonged." (PMID 29651226, 2018). "Metastatic xenograft model displayed decreased expression levels of RUNX3 and TGF-β and higher CpG methylation levels, bigger tumor size and shorter survival time, all which were restored by treatment with a methylation inhibitor." (PMID 29651226, 2018). "Results displayed that miR-544 overexpression in vivo promoted tumor growth, downregulated NCR1 and reduced RUNX3 expression." (PMID 29636640, 2018). "Virus-specific and tumor-specific TRM cells in different tissues and settings require Runx3 for development, exemplifying Runx3 as an important transcriptional regulator of TRM cells." (PMID 30131803, 2018). "The current analyses comprising all eligible articles revealed that promoter methylation of the p16, CDH1, RUNX3, MLH1, RASSF1A, p15, APC, GSTP1, Reprimo, and MGMT was significantly higher in blood samples of patients with GC compared with non-tumor controls." (PMID 29100425, 2017). "Our results also suggest that the transcriptional regulation of FOXP3 is controlled by three transcription factors, SMAD3, GATA3, and RUNX3, in a concerted manner involving CNSs and promoter regions of FOXP3 in tumor-induced CD8+ Treg cells." (PMID 28487507, 2017). "While there is no consensus on a gene panel to determine the CIMP status of a tumour, one of the most commonly used is the Weisenberger panel of genes comprising of CACNA1G, NEUROG1, RUNX3, SOCS1 and IGF2." (PMID 28351398, 2017). "To study the involvement of RUNX3 in FOXP3 transcription we transfected CD8+ T cells with control- or RUNX3-siRNA and then cultured these cells in in vitro tumor microenvironment." (PMID 28487507, 2017). "In PTCs, RUNX3 hypermethylation and TSHR hypomethylation were reported as related to tumor recurrence." (PMID 28938489, 2017).
tumor (continued). "Multiple tumor-related genes are found to be commonly methylated in tissue samples in GC, such as p16, CDH1, RUNX3, MLH1, RASSF1A, p15, APC, DAPK, GSTP1, Reprimo, and MGMT etc.." (PMID 29100425, 2017). "The cumulative results show the intricate transcriptional regulation of FOXP3 is controlled by three transcription factors, SMAD3, GATA3, and RUNX3, involving CNSs and promoter regions of FOXP3 in tumor-induced CD8+ Treg cells." (PMID 28487507, 2017). "To determine a lncRNA regulates BC by mediating the expression of tumor suppressor gene via DNA methylation, we firstly chosen and tested three tumor suppressor genes: RASSF1A, RUNX3 and DBCCR1." (PMID 27777512, 2016). "The subgroup meta-analysis by geographical populations was also performed for p16, APC, RUNX3 and PRDM2 between HCC tumor tissues and normal tissues." (PMID 27835605, 2016). "In order to elucidate the role of RUNX3 as a TSG we evaluated the expression of ARID1A, a well-known TSG; ARID1A expression was lost in 12.5% of the tumor samples, which agrees with previously published results." (PMID 27566570, 2016). "Subgroup meta-analysis by geographical populations was performed for p16, RASSF1A, GSTP1, APC, RUNX3, SOCS1 and PRDM2 between HCC tumor tissues and adjacent tissues." (PMID 27835605, 2016). "Runt-related transcription factor 3 (RUNX3) is a member of the RUNX family and participates in normal physiological, as well as pathological, processes of the immune system, in tumor formation and in other disorders." (PMID 26104385, 2015). "On the other hand, miR-130b has been shown to be highly expressed in CD133+ tumor-initiating cells in HCC and to directly target the well-known tumor suppressor RUNX3, suggesting the prominent oncogenic role of miR-130b in hepatocarcinogenesis." (PMID 25688372, 2015). "As it appears that two or even the three RUNX proteins are often co-expressed in tumor cells, how does the phosphorylation of RUNX1 and RUNX3 by AKT modulate the effects of AKT-mediated RUNX2 phosphorylation on tumor progression?" (PMID 26204939, 2015). "The RUNX3 protein is another transcription factor that was inversely correlated with tumor progression and worse prognosis in ACC possibly because RUNX3 is a known tumor suppressor gene." (PMID 26359351, 2015). "High copy RIS mapping to Runx2 or Runx3 were almost ubiquitous in, but exclusive to, CD2-MYC tumours (P = 0.0001, Fisher's Exact Test)." (PMID 24586197, 2014). "These repressive modifications were increased by hypoxia in the promoter regions of tumour suppressor genes such as RUNX3 and MLH1 which correlated with their silencing, potentially promoting tumour progression." (PMID 25949794, 2014). "RUNX3 belongs to the RUNX family of transcriptional factors, and has been found to correlate with depth of tumor invasion, lymph node and distant metastasis." (PMID 25202403, 2014). "Other highly enriched TFs that regulate proliferation and transformation (tumor supressors) are ANP32A and RUNX3." (PMID 25649207, 2014). "RUNX3 is a downstream target of the transforming growth factor-β (TGF-β) pathway, which is considered a tumor suppressor pathway, as components are frequently altered in cancers, especially those of the gastrointestinal tract." (PMID 23637848, 2013). "After inclusion of the tumor suppressor RUNX3, the DEABM replicated the rate of ER-receptor positive tumor incidence with striking accuracy." (PMID 23704974, 2013). "Similar to other tumor suppressor genes, some of the alterations in RUNX3 are due to the LOH of chromosome 1p36, where RUNX3 is located." (PMID 21205319, 2011). "RUNX3 is known as a nuclear effector of the functional BMP/TGF-ß pathways, and a key tumor suppressor gene in the gastric epithelium." (PMID 19521519, 2009). "Runt-related transcription factor 3 (RUNX3) is a tumor suppressor of cancer and appears to be an important component of the transforming growth factor-beta (TGF-ß)-induced tumor suppression pathway." (PMID 19521519, 2009).
tumor (continued). "Although the proximal portion of the CpG islands was largely unmethylated in both the normal and tumor DNAs, the CpG islands of the MLH1 and RUNX3 genes was hypermethylated in most tumor tissues with a MSI (MLH1) and LOH-B (RUNX3), respectively." (PMID 16827945, 2006). "We have shown that many tumour suppressor and tumour-related genes, such as APC, DAP-kinase, DCC, E-cadherin, hMLH1, p16, RASSF1A and RUNX3, exhibit promoter hypermethylation in both neoplastic and non-neoplastic gastric epithelia at variable frequencies." (PMID 15138487, 2004). "Interestingly, we also observed a negative correlation between CTU2 expression and the gene dependency of canonical tumor suppressor genes, such as PTEN and RUNX3, with these genes becoming less essential in CCLE-included cancer cell lines overexpressing CTU2." (PMID 40375999, 2025). "Meanwhile, Runx3 suppresses the expression of T‐bet and Eomes, as well as KLF2, and downregulates tissue‐egress molecules including S1PR1, CD62L and CCR7, further facilitating the retention of CD8+TRM cells within the tumor microenvironment (TME)." (PMID 40066223, 2025). "RUNX3 signature was elevated in RCC samples, compared non-tumor tissues (P < 0.001)." (PMID 38172737, 2024). "The results led to a point that RUNX3 pathway could regulate CD8 + T cell function in TME, thus impact tumor microenvironment and IO/TKI benefit." (PMID 38172737, 2024). "RUNX3, which is hypermethylated in pan-negative cases, is known to function as a tumor suppressor gene that inhibits Wnt signaling by inhibiting β-catenin/Tcfs, and its expression is known to be regulated by DNA methylation." (PMID 38433247, 2024). "Among the genes that showed a trend toward hypermethylation in the pan-negative cases were RUNX3, a known tumor suppressor gene, and CCNA144, which has been reported to correlate with treatment response to doxorubicin and 5-fluorouracil." (PMID 38433247, 2024). "SCRIPro could accurately predicts well-known master regulators including SPI1, IRF1, FLI1, and STAT2 for mono/macrophages, GATA3, RUNX3, SMARCA4, JUND, and MYB for T-cells, PAX5, BCL2, and IRF4 for B and tumor B-cells." (PMID 39024032, 2024). "In a mouse model of melanoma, it was observed that CD8+ TIL lacking Runx3 exhibited reduced aggregation within tumor tissue, resulting in accelerated tumor progression and unfavorable prognosis." (PMID 38426090, 2024). "These database findings corroborate the dual prognostic implications of RUNX1, underline the primary negative prognostic influence of RUNX2, and validate the tumor-suppressive role of RUNX3." (PMID 38430423, 2024). "Therefore, we searched for genes whose expression levels show similar patterns to the trend of tumor growth: it is expressed at higher levels in exp‐CAF 544 cells than in exp‐CPF 522 cells and decreased by RUNX3 knockdown in the former." (PMID 37641472, 2023). "The rare tumor cell that exhibited moderate nuclear RUNX3 expression coincided with very weak or no discernible MYC protein expression." (PMID 37400551, 2023). "Finally, dendritic cell infiltration was detected in 24 tumor types for RUNX1, in 24 types for RUNX2, and in 26 types for RUNX3." (PMID 36321611, 2023). "Indeed, we confirmed RUNX3 expression is significantly higher in NKTL cell lines and NKTL patient tumor samples when compared to normal NK cells (p = 2.8E-05 and 1.1E-04, respectively)." (PMID 37032358, 2023).
tumor (continued). "The molecular analysis of tumor specimens acquired from patients who did not undergo chemotherapy or radiotherapy revealed that RUNX3 protein and RUNX3 transcript levels were reduced compared with normal tissue." (PMID 36901967, 2023). "RUNX3 is an important mediator during lymphocyte differentiation into CD4+ and CD8+ cytotoxic T -lymphocytes (CTL) and natural killer cell progenitors into natural killer (NK) cells, and is thus likely pivotal in the development of anti-tumor immunity." (PMID 36900240, 2023). "Because RUNX3 is abundantly present in exp‐CAF 544 cells, we next investigated whether RUNX3 contributes to their tumor‐promoting ability." (PMID 37641472, 2023). "RUNX3 can reprogram T-cell genes to promote the expression of genes related to T-cell settlement in tissues, thus promoting the accumulation of CAR-T cells in tumor tissues." (PMID 36979400, 2023). "Furthermore, tumor epithelial expression of SMAD4 in cytoplasm (HR 0.58, 95% CI 0.43–0.80, p < 0.001) and RUNX3 in nucleus (HR 0.62, 95% CI 0.45–0.84, p = 0.002) were independent positive predictors of DSS." (PMID 36900240, 2023). "Furthermore, extensive correlations between IRS-1 and IRS-2, RUNX3 and SMAD4 in tumor and stroma, were observed (0.15 < r < 0.60)." (PMID 36900240, 2023). "We determined the expression of RUNX3 and E-cadherin in tumor tissues and adjacent normal tissues of 30 CCRCC patients; established cultured CCRCC cells with the overexpression of RUNX3; and examined the in vivo tumorigenic function of RUNX3 in a nude mouse xenograft model of CCRCC." (PMID 36518886, 2022). "RUNX3 is recognized as the master transcription factor of CD8+ T cell differentiation and function, but only a handful of studies have revealed its direct role in CTL-mediated anti-tumor immunity." (PMID 36231078, 2022). "Ectopic RUNX3 could be used to compensate its defects in GC and as a competitor for TEAD binding, resulting in tumour-regressing effects." (PMID 35565411, 2022). "It will be, therefore, of great interest to examine how RUNX3 can be experimentally utilized to optimize the proinflammatory functions of Th1 and its infiltration into the tumor microenvironment (TME) to suppress tumor growth." (PMID 36231078, 2022). "It is, however, unknown whether RUNX3 functions in ILC1/3-mediated anti-tumor immune responses; however, all the ILC subsets are detectable within TILs albeit with undefined roles in the tumor microenvironment (TME)." (PMID 36231078, 2022). "In contrast, CD8+ T cells lacking Runx3 expression did not accumulate in the tumor microenvironment, resulting in uncontrolled tumor growth and reduced survival." (PMID 33467606, 2021). "EOC patients with methylation of CAMK2N1 or RUNX3 have a shorter overall survival than patients without methylation of these genes independently from FIGO staging or tumor resection status." (PMID 33482905, 2021). "We demonstrated that RUNX3 does not have prognostic value or a positive prognostic value, even though it is usually regarded as a tumor suppressor gene." (PMID 33672337, 2021). "This pattern of tumor growth was similar to that observed with overexpression of RUNX3 WT without G9a." (PMID 33116296, 2021). "RUNX3 is upregulated in CD44+ T cells, which serves as immunosuppressive role in tumor." (PMID 35187044, 2021). "Further results of ChIP assays revealed that SNHG22 could recruit EZH2 to the promoter regions of multiple tumor suppressor genes (E-cadherin, EAF2, ADRB2, rap1GAP and RUNX3), and modulating H3K27me3 levels to repress their transcription." (PMID 34663788, 2021).
tumor (continued). "In consideration of the fact that stem–like traits were intricately correlated with tumour metastasis, relapse and resistance to chemical agents, we suggested that PIM1 could promote tumour metastasis by facilitating RUNX3 nuclear dislocation." (PMID 32307917, 2020). "We speculate that TrkB might attenuate the BMP inhibition of tumor growth by regulating BMPRI expression and thereby deplete the RUNX3 protein." (PMID 32731498, 2020). "RUNX3 belongs to the family of Runt‐related transcription factors (RUNX), and the RUNX family was identified to play a pivotal role in both normal development and neoplasia." (PMID 32307917, 2020). "Runx3 is a well-established regulator of CD4+ and CD8+ T cells, so we assessed whether miR-301a deletion alters tumor stromal immune responses." (PMID 31122259, 2019). "The results of this study indicate that c-MET and RUNX3 are differentially expressed in GCs compared with normal adjacent gastric mucosa and found a correlation between low RUNX3 levels and c-MET overexpression and tumor recurrence." (PMID 30871613, 2019). "Meanwhile, miR-210 released from adipose-derived stem cells promoted the proliferation, invasion, and migration of endothelial cells by targeting runt-related transcription factor 3 (RUNX3), suggesting that exosomal miR-210 may mediate tumor angiogenesis." (PMID 31500658, 2019). "Further studies revealed that miR-301a deficiency in the tumor microenvironment effectively reduced tumor metastasis by elevating Runx3 and recruiting CD8+ T cells, whereas miR-301a knockdown in tumor cells themselves restrained cell migration by elevating Runx3 expression." (PMID 31122259, 2019). "In this study, we demonstrate that re-expression of RUNX3 in KGN cells promotes cell growth, colony formation, and migration in vitro, as well as tumor formation in mice, which likely involves regulating the expression of cyclin D2 and p27Kip1, two key cell cycle regulators in GCT." (PMID 31311113, 2019). "Patients surviving more than 24 months were more likely having tumours without RUNX3 gene methylation than patients surviving less than 24 months period." (PMID 31467531, 2019). "RUNX3 translocates into the nucleus in response to TGF-β signal transduction, and may function in the nucleus as tumor suppressor and transcriptional regulator." (PMID 29651226, 2018). "In a preclinical model of melanoma, CD8+ TIL not expressing Runx-3 did not accumulate in tumor microenvironment, resulting in uncontrolled tumor growth and low survival." (PMID 30100906, 2018). "Of therapeutic importance, Runx3 overexpression in LCMV-specific CD8 T cells promoted T cell access to viral antigen-expressing B16 tumors, enforced the acquisition of a TRM phenotype in tumors, and enhanced T cell anti-tumor activity." (PMID 30555481, 2018). "CD8 T cells with reduced levels of Runx3 expression failed to constrain tumor growth, further implicating a tumor surveillance role for tissue-resident CTLs." (PMID 30298068, 2018). "LNK cells transfected with miR-544 mimic significantly led to enlargement of tumor volumes (P < 0.05), the enhancement of miR-544 and decrease of NCR1 expression at mRNA levels (P < 0.05) and the reduction of NCR1 and RUNX3 protein expression (P < 0.05)." (PMID 29636640, 2018). "They concluded that absence of RUNX3 expression in normal epithelium undermines the tumor suppressor role for RUNX3." (PMID 29201108, 2017). "We did not discover significant correlations between staining of RUNX3 and patient sex, age, tumor volume, or tumor grade." (PMID 29254144, 2017). "Why RUNX3, which is known as an important tumor suppressor, does not exert any notable growth inhibitory effect in our cell lines?" (PMID 29201108, 2017).